GAS5 (growth arrest specific 5)
Diseases named in the same sentence as GAS5 in open-access papers (continued):
Sharing a sentence is not in itself a finding about the gene and the disease.
multiple sclerosis (8 papers, 2018 to 2025). A progressive autoimmune disorder affecting the central nervous system resulting in demyelination. "Regarding the correlation between lnc‐GAS5 expression and immune‐disease severity, a positive correlation has been found between lnc‐GAS5 expression and the Expanded Disability Status Scale score for multiple sclerosis." (PMID 34473845, 2021). "The aim of the present study was to investigate the role of lncRNA GAS5 and its downstream target Nuclear Receptor Subfamily 3 Group C Member 1(NR3C1) in the pathogenesis of multiple sclerosis (MS), and to define the role of GAS5 in the regulation of NR3C1 expression." (PMID 30276165, 2018).
Parkinson disease (8 papers, 2017 to 2025). A progressive degenerative disorder of the central nervous system characterized by loss of dopamine producing neurons in the substantia nigra and the presence of Lewy bodies in the substantia nigra and locus coeruleus. "GAS5 and MALAT1 have a close association with Parkinson’s disease and aging and are involved in neurodegeneration." (PMID 36710930, 2022). "Furthermore, the expression profiles of the lncRNAs Malat1, Neat1, and Gas5 were significantly dysregulated in the Parkinson's disease model, with Malat1 and Neat1 showing notable upregulation, which has been associated with enhanced oxidative stress and neuroinflammation." (PMID 41208834, 2025). "GAS-5 is correlated with NLRP3 activation and the progression of cognitive impairment in Parkinson’s disease." (PMID 40257540, 2025). "GAS-5 is correlated to NLRP3 activation and the progression of cognitive impairment in Parkinson’s disease." (PMID 40257540, 2025).
breast tumor (7 papers, 2014 to 2025). "A previous study demonstrated that GAS5 expression was negatively correlated with that of miR-21 in breast tumor specimens and cell lines." (PMID 40486272, 2025). "Zhang and colleagues discovered a regulatory loop of reciprocal repression between GAS5 and miR-21 expression in breast tumor specimens and cell lines." (PMID 40486272, 2025). "On the other hand, GAS5 lncRNA acts as an oncosuppressor, being downregulated in breast tumors and leading to apoptosis and block of proliferation in vitro." (PMID 27447964, 2017). "However, in human breast tumor samples, the transcription level of GAS5 are significantly reduced, which is statistically significant in stage I and II cancers 35, prompting the decrease of GAS5 expression as an early event of tumorigenesis." (PMID 35813295, 2022).
endometrial cancer (7 papers, 2015 to 2025). Primary or metastatic malignant neoplasm involving the endometrium (mucous membrane that lines the endometrial cavity). "Reduced expression of GAS5 in tumor-associated macrophages (TAMs) in endometrial cancer has been observed." (PMID 37511248, 2023). "As PTEN was the most commonly mutated gene identified in endometrial carcinoma, we investigated the effect of GAS5 on the expression of PTEN." (PMID 26511107, 2015). "As a tumor suppressor, GAS5 enhances PTEN expression by inhibiting miR-103 expression in endometrial cancer." (PMID 27034004, 2016). "In this study, we identified that GAS5 was down-regulated in endometrial cancer cells and stimulated the apoptosis of endometrial cancer cells." (PMID 26511107, 2015). "Through transfecting GAS5 plasmid or si-GAS5 into endometrial cancer cells, the mRNA level of miR-103 were significantly decreased or increased, respectively." (PMID 26511107, 2015). "According to the result of real-time reverse-transcriptase polymerase chain reaction (RT-PCR) and flow cytometry analysis, we identified that GAS5 was down-regulated in endometrial cancer cells and stimulated the apoptosis of endometrial cancer cells." (PMID 26511107, 2015). "And we found that the expression of PTEN was up-regulated when endometrial cancer cells overexpressed GAS5." (PMID 26511107, 2015). "Taken together, we found that GAS5 involved in the up-regulation of PTEN in endometrial cancer cells through inhibiting the expression of miR-103." (PMID 26511107, 2015). "GAS5 overexpression has also been demonstrated to repress endometrial cancer formation in immunodeficient mice models through PTEN/AKT signaling and directly repressing oncogenic yes-associated protein 1 (YAP1) in tumor-associated macrophages, transforming them into an anti-tumor phenotype." (PMID 39941145, 2025). "The decreased expression profile of TAM-associated lncRNA Growth Arrest Specific 5 (GAS5) was correlated with the negative prognosis in endometrial cancer." (PMID 40176927, 2024). "MiR-21 as an oncogene inhibits the suppressive effect of GAS5 in endometrial cancer cells." (PMID 37511248, 2023). "An important pathway in the pathogenesis of endometrial cancer is the GAS5-miR-103-PTEN pathway." (PMID 37511248, 2023). "We found that miR-103 mimic could decrease the mRNA and protein levels of PTEN, and GAS5 plasmid may reverse this regulation effect in endometrial cancer cells." (PMID 26511107, 2015). "In summary, we demonstrate that GAS5 acts as an tumour suppressor lncRNA in endometrial cancer." (PMID 26511107, 2015). "In addition, the expression of PTEN was increased in endometrial cancer cells transfected with GAS5 plasmid." (PMID 26511107, 2015). "In addition, the expression of PTEN was up-regulated when endometrial cancer cells overexpressed GAS5." (PMID 26511107, 2015). "In this study, we also found that the mRNA level of GAS5 was reduced in endometrial cancer cells." (PMID 26511107, 2015). "The results of this study may aid the understanding of the effects of GAS5 in the tumor suppression and progression of endometrial cancer." (PMID 26511107, 2015). "In summary, we demonstrate that GAS5 acts as an tumor suppressor lncRNA in endometrial cancer." (PMID 26511107, 2015). "Manipulation of GAS5 axis expression might represent a novel potential therapeutic target for endometrial cancer treatment." (PMID 26511107, 2015). "However, the expression and mechanism of action of GAS5 were largely poor understood in endometrial carcinoma." (PMID 26511107, 2015). "In addition, GAS5 might reverse the regulation effect of miR-103 on PTEN in endometrial cancer cells." (PMID 26511107, 2015). "Finally, we found that miR-103 mimic could decrease the mRNA and protein levels of PTEN through luciferase reporter assay and western blotting, and GAS5 plasmid may reverse this regulation effect in endometrial cancer cells." (PMID 26511107, 2015).
endometrial cancer (continued). "Being contrary to the tumour suppressor function of GAS5 and PTEN, miR-103 was found to stimulate growth and invasion in endometrial cancer cell lines." (PMID 26511107, 2015). "LncRNAs that play a role in tumor suppression in endometrial cancer include: FER1L4, GAS5, MEG3, RP11-395G23.3, LA16C −313D11.11, Xist, Linc ROR, MALAT1, HOTAIR, OVAL, SRA, etc., However, the mechanism of cuproptosis-associated LncRNAs in endometrial cancer is still unclear." (PMID 37124623, 2023). "Through inhibiting the expression of miR-103, GAS5 significantly enhanced the expression of PTEN to promote cancer cell apoptosis, and, thus, could be an important mediator in the pathogenesis of endometrial cancer." (PMID 26511107, 2015).
pneumonia (7 papers, 2021 to 2024). An acute, acute and chronic, or chronic inflammation focally or diffusely affecting the lung parenchyma, caused by an infection in one or both of the lungs (by bacteria, viruses, fungi, or mycoplasma.). "By means of the miR-455-5p/SOCS3 pathway,GAS5 boosts M1 macrophage polarization in adolescent pneumonia." (PMID 35880572, 2022). "RT-qPCR experiments illustrated that plasma GAS5 level was downregulated in pneumonia patients (P < 0.01)." (PMID 34758804, 2021). "GAS5 and miR-155 expression levels in plasma samples from both pneumonia (n = 62) and healthy controls (n = 62) were analyzed." (PMID 34758804, 2021). "GAS5 and miR-155 levels in plasma samples from pneumonia patients and controls were detected using RT-qPCR." (PMID 34758804, 2021). "It has been well established that lung inflammation promotes the aggregation of pneumonia, suggesting the potential involvement of GAS5 in pneumonia." (PMID 34758804, 2021). "Previous studies have shown that lncRNA GAS5 and miR-155 play opposite roles in responses to lung inflammation, a key player in pneumonia, suggesting the involvement of GAS5 and miR-155 in pneumonia." (PMID 34758804, 2021). "Lung inflammation participates in childhood pneumonia, indicating the involvement of GAS5 and miR-155 in pneumonia." (PMID 34758804, 2021). "The study aimed to analyze the potential interaction between GAS5 and miR-155 in childhood pneumonia." (PMID 34758804, 2021). "GAS5 has a role in pneumonia by regulating the microRNA-222-3p/TIMP3 axis." (PMID 38407972, 2024). "For instance, in childhood pneumonia, lnc‐GAS5 might regulate the Treg/Th17 imbalance by targeting the miR‐217/STAT5 axis." (PMID 35325494, 2022). "Our studies on the role of GAS5 and miR-155 in pneumonia using the HBEpC model showed that GAS5 might downregulate miR-155 by increasing its methylation, thereby suppressing cell apoptosis, promoting SHIP-1 expression, and possibly decreasing inflammation." (PMID 34758804, 2021). "GAS5 and miR-155 were inversely correlated across both pneumonia samples and control samples." (PMID 34758804, 2021). "GAS5 was downregulated in pneumonia, and miR-155 was upregulated in pneumonia." (PMID 34758804, 2021). "We found that GAS5 and miR-155 expression was altered in pneumonia, and GAS5 might increase miR-155 RNA gene methylation to downregulate its expression, thereby inhibiting LPS-induced HBEpC apoptosis." (PMID 34758804, 2021). "GAS5 may participate in childhood pneumonia by inhibiting cell apoptosis and promoting SHIP-1 expression via downregulating miR-155." (PMID 34758804, 2021). "This study analyzed the interactions between GAS5 and miR-155 in pneumonia." (PMID 34758804, 2021). "This study is the first to report to show GAS5 downregulation in pneumonia." (PMID 34758804, 2021). "In conclusion, GAS5 was downregulated in pneumonia, and miR-155 was upregulated in pneumonia." (PMID 34758804, 2021). "LncRNA growth-arrest-specific 5 (GAS5) shifts macrophages toward the M1 subtype from the M2 subtype by acting as a miR-455-5p ceRNA regulator that promotes SOCS3 expression during childhood pneumonia." (PMID 34502451, 2021). "Indeed, the role of GAS5 in the pathogenesis of pneumonia has been confirmed by emerging evidence." (PMID 36685535, 2022). "Therefore, we also explored the interactions of SHIP-1 with GAS5 and miR-155 in pneumonia." (PMID 34758804, 2021). "Therefore, GAS5 may play a protective role in pneumonia, possibly by suppressing LPS-mediated cell apoptosis." (PMID 34758804, 2021). "Thus, we analyzed the potential interaction between GAS5 and miR-155 in pneumonia." (PMID 34758804, 2021). "We also observed an inverse correlation between GAS5 and miR-155 across plasma and BALF samples from both pneumonia patients and healthy controls." (PMID 34758804, 2021). "Correlations between GAS5 and miR-155 levels in plasma and BALF across both pneumonia samples and control samples were analyzed by linear regression." (PMID 34758804, 2021).
pneumonia (continued). "Our results suggested that GAS5 expression was downregulated, and miR-155 expression was upregulated in both BALF and plasma of pneumonia patients compared with the healthy controls." (PMID 34758804, 2021). "In addition, GAS5 and miR-155 mRNA levels in BALF were analyzed in both pneumonia (n = 62) and healthy controls (n = 62) using RT-qPCR." (PMID 34758804, 2021).
polycystic ovary syndrome (7 papers, 2019 to 2022). A disorder that manifests as multiple cysts on the ovaries. "Downregulation of GAS5 has also been implicated in polycystic ovary syndrome (PCOS), which is a disease tightly connected with insulin resistance and inflammation pathogenesis, comparable to DM." (PMID 31847392, 2019). "Similarly, lncRNA GAS5 expression was significantly lower in the peripheral blood of patients with polycystic ovarian syndrome with IR and was negatively correlated with the IR resistance index of the patients." (PMID 35178132, 2022). "LncRNA growth arrest-specific 5 (GAS5) is upregulated in the plasma of patients with polycystic ovary syndrome (PCOS)." (PMID 34680193, 2021). "It is known that cell apoptosis and hormone response play crucial roles in polycystic ovary syndrome (PCOS), indicating the potential involvement of GAS5 in PCOS." (PMID 33308258, 2020). "In contrast, in disorders associated with IR, such as polycystic ovary syndrome (PCOS), GAS5 expression was found to be downregulated: GAS5 expression was decreased in the serum of PCOS patients with IR, and the researchers found a negative correlation between HOMA-IR and GAS5 expression." (PMID 34298896, 2021).
psoriasis (7 papers, 2018 to 2025). An autoimmune condition characterized by red, well-delineated plaques with silvery scales that are usually on the extensor surfaces and scalp. "Moreover, the existence of a correlation between the plasmatic concentrations and psoriasis severity turns lncRNA GAS5 into a promising marker not only for diagnosing psoriasis but also for assessing the severity of the disease." (PMID 40725772, 2025). "Several lncRNAs are upregulated in psoriasis, such as MSX2P1, XIST, FABP5P3, KLDHC7B-DT, or SPRR2C, whereas MEG3, GAS5, PRINS or NEAT1 are downregulated in psoriasis." (PMID 38256115, 2024). "Other upregulated lncRNA in psoriasis are MIR31HG, MSX2P1, XIST, FABP5P3, KLDHC7B-DT, or SPRR2C; whereas, MEG3, GAS5, PRINS or NEAT1 are downregulated in psoriasis." (PMID 37628670, 2023). "LncRNAs have been revealed to participate in the pathogenesis of psoriasis, including MEG3, GAS5, and MIR31HG." (PMID 35586566, 2022). "Other lncRNAs that have revealed roles in psoriasis include lncRNA RP6-65G23.1, lncRNA MSX2P (cytoplasmic lncRNA Msh homeobox 2 pseudogene 1), and lncRNA GAS5 (growth arrest specific 5)." (PMID 35559048, 2022).
renal fibrosis (7 papers, 2022 to 2025). A final common manifestation of a wide variety of chronic kidney diseases characterized by glomerulosclerosis and tubulointerstitial fibrosis. "Spearman’s rank correlation analysis revealed a robust positive association between plasma GAS5 and renal fibrosis severity (r = 0.502, 95% CI 0.43–0.58, p < 0.001), whereas urinary GAS5 exhibited a stronger inverse correlation (r = −0.646, 95% CI −0.71–−0.58, p < 0.001)." (PMID 40685500, 2025). "However, not only implicated in cancer development, a functional association of GAS5 with renal fibrosis, a pathological feature of CKD characterized by an excessive accumulation and deposition of extracellular matrix (ECM) components 29, was also proposed." (PMID 39239549, 2024). "The results showed that, compared to eGFR and TGF-β1, urinary GAS5 had a higher AUC, suggesting that urinary GAS5 has a superior predictive capability for renal fibrosis." (PMID 40685500, 2025). "The present study demonstrates that the expression of plasma GAS5 and urinary GAS5 in renal fibrosis were in opposite trends: plasma GAS5 upregulation and urinary GAS5 suppression." (PMID 40685500, 2025). "While plasma GAS5 upregulation and urinary GAS5 suppression reflect inverse expression patterns in renal fibrosis, urinary GAS5 emerges as the dominant noninvasive biomarker due to its superior diagnostic performance (AUC = 0.868) and clinical accessibility." (PMID 40685500, 2025). "Preclinical studies demonstrate that GAS5 expression is downregulated in renal fibrosis models, including unilateral ureteral obstruction (UUO) and diabetic nephropathy, correlating with extracellular matrix (ECM) accumulation." (PMID 40685500, 2025). "Further analysis was conducted using ROC curves to evaluate the predictive value of GAS5 for renal fibrosis." (PMID 40685500, 2025). "Plasma GAS5 levels increased with renal fibrosis severity, whereas urinary GAS5 exhibited progressive suppression." (PMID 40685500, 2025). "While our study provides novel insights into urinary GAS5 as a potential biomarker for renal fibrosis, several limitations warrant consideration." (PMID 40685500, 2025). "Our prior studies have demonstrated that GAS5 inhibits renal fibrosis via microRNA-mediated pathways, including suppression of miR-21 activity and regulation of the Smad3/miRNA-142-5p axis in TGF-β signaling." (PMID 40685500, 2025). "Through diverse molecular mechanisms (e.g. sponging specific microRNAs, suppressing ECM enzymes, and regulating fibrogenic gene transcription), this inhibitory effect of GAS5 on renal fibrosis was consistently detected in various studies 30, 31, 49-51." (PMID 39239549, 2024). "Growth arrest-specific 5 (GAS5), a long noncoding RNA (lncRNA) gene, has been recently shown to regulate renal fibrosis." (PMID 39239549, 2024). "A previous study demonstrated that GAS5 attenuated renal fibrosis by modulating the Smad3/miRNA-142-5p axis." (PMID 36918759, 2023). "Furthermore, the AUC of urinary GAS5 was also high in the three renal fibrosis subgroups, especially higher in the more severe renal fibrosis group." (PMID 40685500, 2025). "ROC analysis demonstrated that urinary GAS5 outperformed eGFR and TGF-β1 in diagnostic accuracy, with higher AUC values, suggesting urinary GAS5 may serve as a potential biomarker for renal fibrosis." (PMID 40685500, 2025). "In the severe renal fibrosis subgroup, the AUC value of urinary GAS5 was as high as 0.956." (PMID 40685500, 2025). "Nonetheless, prior investigations were constrained by limited sample sizes and concentrated exclusively on the correlation between GAS5 levels in plasma and urine and the progression of CKD, neglecting to explore its potential association with the severity of renal fibrosis in these patients." (PMID 40685500, 2025). "AUCs of urinary GAS5 were even higher in moderate and severe renal fibrosis group." (PMID 40685500, 2025). "Silencing of lncRNA GAS5 reduced renal fibrosis via inhibition of miR-96-5p." (PMID 36313695, 2022).